CAT (catalase)
Diseases named in the same sentence as CAT in open-access papers (continued):
Sharing a sentence is not in itself a finding about the gene and the disease.
cancer (continued). "Crucially, cancer cells can adapt to elevated ROS levels by increasing the activity of endogenous antioxidant systems, such as glutathione (GSH), superoxide dismutase (SOD), catalase (CAT), and the thioredoxin (Trx) system." (PMID 41011117, 2025). "Based on this evidence, we co-incubated cancer cells (MDA-MB-453) with AA and catalase." (PMID 40940976, 2025). "The discovery of specific, non-toxic CAT inhibitors presents significant potential for use in cancer co-therapy." (PMID 41256015, 2025). "Thus, decreased CAT activity results in the accumulation of H2O2, which acts as a secondary messenger to promote cell proliferation, DNA damage, and angiogenesis in cancer cells." (PMID 40722961, 2025). "However, when these levels rise as a result of cancer, the activity of these enzymes, including SOD, and CAT decreases, while oxidative stress marker MDA increases." (PMID 40670469, 2025). "However, CAT reduces H2O2 levels induced by paclitaxel, thereby interfering with its pro-oxidant anti-cancer effects and promoting cancer cell survival." (PMID 40722961, 2025). "These advanced nanozymes possess the capacity to manifest a range of activities, including peroxidase (POD), catalase (CAT), superoxide dismutase (SOD), and glutathione oxidase (GSHOx), thereby facilitating effective cancer treatment through direct modulation of the TME." (PMID 40969388, 2025). "On the other hand, ErSA and EpSH extracts were significantly more active for catalase on cancer cell lines than nontumor-treated cells." (PMID 38218817, 2024). "Some cellular defensive proteins, such as catalase, superoxide dismutase (SOD), thioredoxin (TRX), and nuclear factor erythroid 2–related factor 2 [NRF-2, a regulator in cellular antioxidant activity], can overcome oxidative stress in cancer cells." (PMID 38666017, 2024). "Various nanozymes, such as catalase (CAT), superoxide dismutase (SOD), oxidase (OXD), and peroxidase (POD) mimetic nanomaterials, have been employed to explore cancer therapies using two distinct therapeutic strategies: direct killing by enhancing ROS levels and indirect killing by depleting ROS." (PMID 38333005, 2024). "In addition, resveratrol promotes antioxidant defense pathways in several cancer cell lines by eliminating free radicals, enhancing the activities of SOD, CAT, and GPX." (PMID 39458478, 2024). "Both derivatives induced the decrease of catalase activity and glutathione levels in cancer cells without targeting the same effect in non-tumoral cells." (PMID 38399259, 2024). "Additionally, we delve into the complex interplay of cellular components, including catalase and NOX1, in defending cancer cells against PDT-induced oxidative and nitrative stress." (PMID 38069213, 2023). "The effects of BQ-SLN3 on antioxidant enzymes, including MDA, SOD, CAT, GSH, and GR, in the treated group were significantly improved and reached the level nearest to that of the control group of rats over the cancer group of rats and the BQ suspension-treated group of rats." (PMID 37765117, 2023). "Herein, Yuan and colleagues constructed cancer cell membrane-wrapped and matrix metallopeptidase-sensitive nanoparticles (CSG@B16F10) to co-deliver oxygen-generating agent catalase (CAT) and CD73siRNA, thus alleviating hypoxia and reshaping T cell exhaustion caused by the CD73-ADO pathway." (PMID 37514008, 2023). "Furthermore, rats treated with OME had better oxidative status represented by significantly higher CAT, SOD, and GPX levels and decreased lipid peroxidation shown by lower MDA levels compared to cancer control rats." (PMID 36826002, 2023). "Treatment of cancer A549 cells with Au NPs of both sizes for 24 h did not significantly affect catalase activity of cells compared to controls." (PMID 35936220, 2022).
cancer (continued). "It not only had catalase/peroxidase-like activity to generate endogenous O2 to relieve hypoxic internal environment, but also had a targeted recognition effect on cancer cells with high CD44 receptor expression, showing good anti-cancer properties effect." (PMID 35711646, 2022). "Cancer cells exhibit a powerful antioxidant system consisting of reductants such as the antioxidant enzymes-superoxide dismutase (SOD), catalase (CAT), glutathione peroxidase (GPX) and the antioxidant agents-nicotinamide adenine dinucleotide phosphate (NADPH) and glutathione (GSH)." (PMID 35081965, 2022). "Specifically, ROS promote the accumulation of anionic charges on the surface of NK cells, limiting their ability to adhere to similarly charged target cancer cells, a defect that can be prevented by antioxidant molecules including superoxide dismutase (SOD) mimetics and catalase (CAT)." (PMID 36319998, 2022). "They found that the combination of CAT@Liposome and H2O2@Liposome could significantly improve the effect of cancer treatment." (PMID 35123493, 2022). "But unlike us, they determined the depletion of SOD and catalase activities in mentioned cancer cell line." (PMID 35936220, 2022). "In addation, CAT, POLE, NTHL1, ATP7B, ISCA2, NDUFA1 and NDUFB2 have also been reported to play a key role in the development of cancers." (PMID 36685880, 2022). "Furthermore, this flavonol inhibits xanthine oxidase (XO) activity and increases the activities of catalase, heme oxygenase‐1 (HO), and superoxide dismutase (SOD) in a wide range of cancer and non‐cancer cells." (PMID 36259115, 2022). "The expression of CAT and SOD2 are involved in antioxidant system in various cancer cells." (PMID 33854627, 2021). "Redox homeostasis in cancer cells is aberrant and its regulation may be under the control of the cell antioxidant defense based on SOD1, CAT, and the glutathione system." (PMID 33924212, 2021). "In our validation case series, we found that CAT protein is expressed at different levels in cancer tissues, but not in normal adjacent ones." (PMID 34320944, 2021). "In several cancer cell lines, SFN-induced cell cycle arrest or cell death was also prevented by alleviating ROS levels, such as by overexpressing catalase, an endogenous antioxidant, or supplementing cells with NAC or (2R, 4R)-4-aminopyrrolidine-2,4-dicarboxylate (ADPC), a ROS inhibitor." (PMID 34854886, 2021). "Catalase can also promote the decomposition of hydrogen peroxide in cancer cells, so that they will not continue to produce toxic free radicals and thus avoid apoptosis." (PMID 33653412, 2021). "Hence, catalase enzymes remain active and decompose the excess H2O2 in cancer cells, so there will be an alternative pathway for CAP-induced cancer cell death." (PMID 34502494, 2021). "Two different therapeutic approaches, direct killing (increasing ROS) and indirect killing (depletion of ROS) have been used to investigate cancer therapeutics using various nanozymes, mainly peroxidase (POD), oxidase (OXD), superoxide dismutase (SOD) and catalase (CAT) mimetic nanomaterials." (PMID 34356639, 2021). "Moreover, Eucheuma cottonii extract displayed the upregulation of antioxidant enzymes such as catalase (CAT), superoxide dismutase (SOD), glutathione peroxidase (GPx) in cancer-induced rats." (PMID 33374738, 2020). "However, there are still controversies regarding the bodily activity of the antioxidant system, including GPX, Catalase, and SOD, in cancer patients." (PMID 33112539, 2020). "To survive, the malignant cells keep the optimal concentrations of superoxide radical and hydrogen peroxide by expressing high activity of superoxide dismutase (SOD) and catalase (CAT), this even leading to the development of chemotherapeutic resistance of the cancer cells." (PMID 33238535, 2020). "Role of Catalase, SOD, and GPx are directly related to cancer." (PMID 32158360, 2020).
cancer (continued). "Our results show that a catalase-dependent reactivation of the two apoptotic pathways of interest is unlikely to contribute to the observed anti-cancer effect of CAP." (PMID 33096638, 2020). "Catalase over-expression (CAT3 cells) increased the resistance of cancer cells to drugs inducing oxidative stress, likely by increasing the antioxidant status of cancer cells." (PMID 32158360, 2020). "Since hypoxic cancer cells often come with a high concentration of H2O2, one of the most effective ways to overcome cellular hypoxia is to decompose H2O2 for the generation of more O2 using Catalse (CAT)." (PMID 33292202, 2020). "Antioxidants such as N-acetylcysteine (NAC) and catalase are able to prevent the ANE- and arecoline-induced toxic events such as COX-2 expression, PGE2, IL-1α, cytotoxicity etc. as well as MMP-9 secretion of SAS cancer epithelial cells in this study." (PMID 31831717, 2019). "Alternatively, an application of antioxidants or membrane-permeant ROS scavengers: superoxide dismutase (PEG—SOD) and catalase (PEG—CAT), which reduces the basal ROS level in cancer cells, abolishes the pro-apoptotic effect of inhibition of mito Kv1.3 channel by the compounds." (PMID 31612103, 2019). "However, in cancer cells, there is acidic pH which promotes SOD mimetic activity of CNPs but inhibits its catalase mimetic activity which results in the accumulation of the huge amount of H2O2 (ROS) in the cancer cell." (PMID 31291944, 2019). "Next, we analyzed the activity of GSH-dependent enzymes (GPx, GST), CAT and MnSOD in order to obtain a comprehensive view of the role of antioxidant machinery in cancer and non-cancerous cell lines." (PMID 30498945, 2019). "Considering the already increased H2O2 production in cancer cells, it may be concluded that simultaneous reduction of CAT and GPx in adenocarcinoma could additionally raise H2O2 level, and thus affect further progression and metastasis of cancer." (PMID 30978928, 2019). "In the current work, ROS generation, lipid peroxidation, detection of H2O2 and NO, the activity of antioxidative enzymes (mitochondrial superoxide dismutase [MnSOD], CAT, glutathione-S-transferase [GST], GPx) as well the status of glutathione in cancer and normal cells have been assessed." (PMID 30498945, 2019). "This enhanced cancer cell killing was dependent upon the catalytic activity of the SOD mimetic and the generation of H2O2, as determined using conditional overexpression of catalase in H1299T cells." (PMID 29351198, 2018). "The generation of ROS in response to TMZ-POH seems to play a crucial role in the cell death process since the blockage of ROS production using the antioxidant N-acetyl-L-cysteine or catalase reversed the TMZ-POH-induced JNK activation, DNA damage, and cancer cell apoptosis." (PMID 26625208, 2016). "Pre-treatment with H2O2 inactivates peroxidases and catalase, resulting in negative staining for peroxidase activity in malignant neoplasms." (PMID 26927177, 2016). "CAT and NAP showed DHE fluorescence decreases by 7% to 15% in cancer cells." (PMID 25715710, 2015). "Since superoxide does not readily transit cell membranes, and since extracellular catalase abolishes ascorbate’s toxicity to cancer cells, hydrogen peroxide appears to mediate, in whole or in part, this toxicity." (PMID 25279352, 2014). "Here it can be emphasized that suppression of cancer cell viability is not envisaged only by catalase inhibition but other pathways contribute to it." (PMID 25025898, 2014). "Extracellular catalase, but not superoxide dismutase, abolishes the toxicity of extracellular ascorbate to cancer cells." (PMID 25279352, 2014). "As the H2O2-detoxifying enzymes, GPx and CAT activities decreased with extract treatment, high levels of H2O2 produced by the increasing SOD activity possibly led to H2O2 accumulation, leading to MCF-7 cancer cell death." (PMID 24517259, 2013).
cancer (continued). "Therefore, we propose that combining ferroptosis, the ICD effect, and CAT oxygen supply with CD47–SIRPα blockade may be an effective strategy for enhancing macrophage phagocytosis and improving cancer immunotherapy." (PMID 40051791, 2025). "Alternatively, cancer cells also cope with ROS by increasing NRF2 signaling and antioxidant enzyme expression (enzymes involved in GSH synthesis, thioredoxin, thioredoxin reductase, sulfiredoxin, peroxiredoxin, GPx, glutathione S-transferases, catalase (CAT) and superoxide dismutase (SOD))." (PMID 39195531, 2024). "Taken together, the anti-cancer effect of carotenoid extracts may be due to the excessive production of pro-oxidant factors such as ROS and MDA, as well as the reduced activity of the antioxidant enzyme activity system, including GR, POD, SOD, GSH, and CAT." (PMID 38539798, 2024). "First, cancer cells may regulate their redox potential to favor their survival, which is determined not only by the amount of SOD but also by the amounts of superoxide anion, catalase, and glutathione peroxidase." (PMID 39417633, 2024). "Several antioxidant enzymes, including biomarkers, superoxide dismutase (SOD), catalase (CAT), glutathione peroxidase (GPx), glutathione-S-transferase (GST), and reduced glutathione (GSH), were verified for their effects on the viability and cytotoxicity of normal and cancer cells." (PMID 36903823, 2023). "The main principle is that MPG nanoparticles exhibit catalase (CAT), glutathione (GSH) peroxidase, and Fenton activities because of the presence of Fe3+/Fe2+ redox pair, so MPG can generate ·OH for CDT and deplete glutathione (GSH) to reduce the antioxidant capacity of cancer cells." (PMID 37631285, 2023). "Notably, cancer cells well adapt to ROS by triggering a powerful antioxidant response mainly driven by glutathione (GSH) and antioxidant enzymes, such as superoxide dismutase, catalase, peroxiredoxins, GSH peroxidases, and thioredoxins." (PMID 37538108, 2023). "Current findings strongly suggest that the ability of ELF-EMF in combination to AgNPs to induce oxidative stress in bacterial and cancer cells via generation of ROS, SOD induction and catalase reduction could be responsible for their antibacterial and anticancer potentials." (PMID 35120563, 2022). "Cancer cells’ decreased ability to neutralize the P-AscH−-induced increase in H2O2 has been shown to be secondary to the decreased expression and activity of enzymes responsible for removing H2O2, including catalase, glutathione peroxidase (GPx), and peroxiredoxins (Prx)." (PMID 35624835, 2022). "Additionally, the down-regulation of the antioxidant enzymes, such as CAT, correlate with high levels of H2O2, which is involved in the activation of the signaling pathways that induce the proliferation, the migration, and the cell invasion of cancer cells." (PMID 36077527, 2022). "Our data suggest that upregulation of CAT and GPx-1 in senescent cancer cells may be a characteristic feature and may help distinguish them from non-senescent cancer cells." (PMID 36230727, 2022). "In HT-29 cells, CBD (30 μM) attenuated cancer cell growth and induced necrosis, accompanied by diminished glutathione (GSH)-to-oxidized-glutathione (GSSG) ratio, level of ascorbic acid (AA), activity of catalase (CAT), and GPx and GR, as well as elevated levels of malondialdehyde (MDA)." (PMID 35741337, 2022). "The surprising result of the present study is the negative correlation between CAT activity and vitamin D in the cancer group, suggesting that some regulatory mechanisms might be involved in the course of the disease." (PMID 34721756, 2021). "We demonstrated clearly, in our experimental model, a significant overexpression of SOD2, GST, CAT, and HO-1 in MPM cells towards HMC, thus confirming the increase in antioxidant defense mediated by Nrf2 and a consequent alteration of redox balance, so increasing the survival of cancer cells." (PMID 33799965, 2021).
cancer (continued). "Early approaches aimed to promote antioxidant activity for anti-cancer effect targeted antioxidants and ROS-scavenging systems, such as superoxide dismutase (SOD), glutathione peroxidases, peroxidoxins, glutaredoxin, thioredoxin, catalase, and nuclear factor erythroid 2-related factor 2 (Nrf2)." (PMID 33707480, 2021). "Despite the importance of metal complexes as antioxidant enzyme inhibitors, no clinical anti-cancer drug targets TrxR, CAT, or Prx currently, which may be due to several major challenges in the field." (PMID 35011380, 2021). "Ideally, the model should be compared and, if necessary, calibrated to experimental results, but to the best of our knowledge, there are no experimental studies for the catalase-dependency of the concentration of generated hydroxyl radicals in the extracellular compartment of cancer cells." (PMID 33096638, 2020). "In this study, we found that generation of ROS is intimately involved in cell cycle arrest induced by AsA and further investigation revealed that the cancer cell growth inhibition, ROS generation, and the cell cycle arrest could be markedly reversed by ROS scavengers, such as GSH, catalase and SOD." (PMID 32992455, 2020). "In human cancer cells exposed to oxidative stress (H2O2), tyrosine kinases c-abl (abelson murine leukemia viral oncogene homolog 1) and c-abl-related gene (Arg) were able to phosphorylate human CAT enzyme at residues Tyr231 and Tyr386 to inhibit the CAT at the enzyme activity level." (PMID 32116797, 2020). "However, the data also indicate that CAT-SKL will not provide added anti-cancer benefit when another oncogene, such as HER2, is the molecular co-target." (PMID 28281569, 2017). "In short, the selective anti-cancer capacity of CAP may be due to the combined effect of multiple cellular factors, such as the enhanced expression of AQPs as well as the decreased expression of specific anti-oxidant enzymes such as catalase in cancer cells." (PMID 27845910, 2017). "To further characterize the liquid-plasma-induced death of cancer cells via ROS or RNS, we determined whether a knockdown or overexpression of the enzymes scavenging reactive species (SOD1/SOD2 and catalase) influenced the liquid-plasma-induced death of cancer cells." (PMID 27364630, 2016). "In different cancer cell lines it has been reported that activation of apoptosis by SFN is highly dependent on ROS generation, as the apoptotic effect could be counteracted with ectopic catalase (Cat) expression." (PMID 24667842, 2014). "In A549 cancer lung cells, the H2O2 response induced by MJ increased the expression of the proapoptotic Bax and Bcl-Xs (although not being that of the antiapoptotic Bcl-2 and Bcl-xL proteins) and this led to apoptosis; this event was inhibited by catalase (a specific inhibitor of H2O2)." (PMID 24648844, 2014). "Thus, the lower CAT activity we recorded might be a consequence of the decreased SOD activity in hyperplastic and cancer patients." (PMID 20030853, 2009). "Some previous studies have shown that in cancer cell lines BTZ can induce ROS28, 29; however, in a recent animal study of myocardial ischemia reperfusion injury, BTZ could reduce ROS by augmenting oxidative stress related protein levels of superoxide dismutase, catalase and glutathione." (PMID 38682650, 2024). "Additionally, while NQO1:CAT was not directly measured, inhibition of catalase and GSH did not lead to sensitization of KEAP1-mutated NSCLC during β-lapachone treatment, while inhibition of TXNRD and SOD1 sensitized cancers." (PMID 36978989, 2023). "Additionally, Catalase (CAT) reprimes the TET1 expression, inhibiting the TARDBP expression by decreasing hydroxymethylation levels in its promoter in MDA-MB-468, MDA-MB-231, SUM149, and HCC70 BC cells, decreasing the formation of mammospheres and Cancer Stem Cells (CSCs)." (PMID 38203443, 2023).